CRP (C-reactive protein)
Diseases named in the same sentence as CRP in open-access papers (continued):
Sharing a sentence is not in itself a finding about the gene and the disease.
myocardial infarction (continued). "Acute phase response associated high-abundance proteins such as C-reactive protein are changed in numerous disease states like myocardial infarction, trauma, and rheumatologic diseases." (PMID 39189262, 2024). "The association between serum interleukin-6 (IL-6) and highly sensitive C - reactive protein (hsCRP) as predictors of the risk factors for Myocardial Infarction." (PMID 38854770, 2024). "Randomization included subjects with a prior acute myocardial infarction associated with a high sensitivity C-reactive protein level of 2 mg or more per liter receiving canakinumab versus placebo." (PMID 36984870, 2023). "Epidemiological and prospective cohort studies have independently reported an association between CRP levels and the risk of stroke, peripheral artery disease, acute myocardial infarction, ischemia, atherogenesis, and sudden cardiac death." (PMID 37298077, 2023). "Rosuvastatin reduced both the LDL and the CRP levels by 50% and 37%, respectively, and was associated with reduced hazard for myocardial infarction, stroke, cardiovascular death, and all-cause mortality." (PMID 37629526, 2023). "Several large studies have confirmed an increased risk of ASCVD, especially myocardial infarction, in those patients with elevated CRP and hs-CRP values." (PMID 36984554, 2023). "It is interesting to note that in STEMI patients, peak CRP levels were higher when compared to NSTEMI patients, drawing attention to the possible role of CRP in risk stratification after myocardial infarction." (PMID 38137807, 2023). "Previous studies have demonstrated the importance of inflammatory risk measured by either hs-CRP or PET as a risk factor for future myocardial infarction and mortality." (PMID 37181800, 2023). "A high CRP level in the blood was reported to be an independent risk factor for myocardial infarction (MI) and predicted poor outcome in peripheral arterial disease (PAD) patients." (PMID 35012677, 2022). "Patients had mild leucocytosis with neutrophilia and mildly elevated C-reactive protein levels, typical of systemic pro-inflammatory status associated with acute myocardial infarction." (PMID 36329042, 2022). "The study showed a decreased risk of HF hospitalization in patients with a previous myocardial infarction and elevated c-reactive protein (CRP) on anti-IL-1 therapy." (PMID 35494989, 2022). "CRP has also been shown to promote cell death and phagocytosis of ischemic/hypoxic cells when underlying acute myocardial infarction." (PMID 35203703, 2022). "Relatively low blood levels at >2 mg/L CRP are associated with an increased risk of heart attack, stroke, diabetes and mortality depending on the concentration that was observed." (PMID 35207331, 2022). "This was confirmed by observations of patients for whom the use of rosuvastatin resulted in a decrease in CRP concentrations with a simultaneous decrease in the risk of myocardial infarction." (PMID 35330458, 2022). "C-reactive protein (CRP) has become one of the most studied biomarkers of inflammation due to the fact that atherothrombosis represents a large majority of acute myocardial infarctions, and CRP is strongly associated with this type of pathogenesis." (PMID 36012430, 2022). "As a result of its association with increased levels of troponin, CRP, and other inflammatory parameters, it has been suggested that it can be used as a biomarker in the early diagnosis of acute myocardial infarction." (PMID 36686140, 2022). "Acute inflammation caused by vessel occlusions can be observed in acute myocardial infarction, with rapidly increasing CRP levels up to >100 mg/L over 2–4 days." (PMID 35207331, 2022). "In the 1950s, C-reactive protein (CRP) was first identified as an inflammatory biomarker for acute myocardial infarction (AMI), and decades later, it was also shown to be associated with cardiac hypertrophy and failure." (PMID 34793333, 2022).
myocardial infarction (continued). "An increased CRP count is also considered as a blood marker of inflammation, which predicts the risk of myocardial infarction and/or cardiac diseases." (PMID 34290770, 2021). "This, in turn, increases the level of C-reactive protein CRP, which increases the risk of a heart attack." (PMID 34831743, 2021). "There was a significantly higher rate of all-cause mortality and myocardial infarction in patients with higher CRP values during follow-up." (PMID 34900087, 2021). "Accordingly, CRP has been shown to upregulate MMPs in acute myocardial infarction while being associated with plaque rupture." (PMID 34428207, 2021). "By lowering CRP levels, it resulted in the loss of correlation of CRP concentrations with myocardial infarct sizes as well as LV function." (PMID 33778017, 2021). "Accumulating evidence also demonstrated the important role of CRP concentration for clinical risk stratification in patients with acute coronary syndrome (ACS) or stable myocardial infarction survivors." (PMID 34109224, 2021). "Actually, the increasing CRP levels, reflecting a severe and overactive inflammation response, were found to be associated with the size of myocardial infarct in clinical or animal study." (PMID 34109224, 2021). "In a multitude of human clinical studies, elevated CRP levels post-myocardial infarction have been shown to be associated with larger infarct size, development of heart failure, adverse LV remodelling, and MVO as evaluated by CMR." (PMID 34571836, 2021). "Some studies tried to recommend CRP as a diagnostic biomarker for myocardial infarction, but low sensitivity and specificity have ruled it out." (PMID 33238444, 2020). "High-sensitivity C-reactive protein (hs-CRP) elevation frequently occurs in acute myocardial infarction (AMI) and is associated with adverse outcomes." (PMID 33081810, 2020). "Elevated C-reactive protein (CRP) levels after myocardial infarction are associated with heart failure and poor prognosis." (PMID 32537679, 2020). "Several studies indicate C-reactive protein (CRP), an acute-phase reactant, and high sensitivity C-reactive protein (hs-CRP) are strongly associated with an increased risk of myocardial infarction." (PMID 33062549, 2020). "Cardiovascular events after an acute myocardial infarction appear to be associated with an initially increased CRP value." (PMID 33238444, 2020). "Elevated serum-CRP-levels after myocardial infarction are associated with “harmful inflammation” and poor outcomes." (PMID 32537679, 2020). "Higher levels of CRP correlated to an increased risk of developing AF in general and after acute myocardial infarction." (PMID 32538434, 2020). "Pertinent to emergency service personnel, elevated levels of circulating IL-6 have been linked to the increased synthesis of C-reactive protein, with both of these markers implicated as predictors of myocardial infarction and arterial disease in healthy men." (PMID 31226144, 2019). "Epidemiological studies have consistently associated raised CRP serum levels with an increased risk of acute myocardial infarction (MI), stroke, and peripheral artery disease." (PMID 31057548, 2019). "We showed that bis(phosphocholine)-hexane and bis(phosphocholine)-octane (unpublished) completely abrogated the enhancement of tissue damage caused by human CRP in the rat acute myocardial infarction model." (PMID 30459761, 2018). "For example, higher CRP values during and after acute myocardial infarction are strongly associated with poor prognosis overall, including more extensive myocardial injury, impaired cardiac function and progression to heart failure." (PMID 30459761, 2018). "One proposal for those at-risk populations has been the inhibition of monomeric-CRP for local treatment of vascular disease and reduction of myocardial infarct size in at-risk areas." (PMID 30154790, 2018).
myocardial infarction (continued). "A prospective study confirmed that hsCRP is an independent predictor of myocardial infarction and continuing high CRP indicates an increased risk of coronary events." (PMID 29409508, 2018). "In a large cohort of patients with acute myocardial infarction, there was a graded positive association between increased CRP and new-onset AF22." (PMID 29118378, 2017). "The present results show that kidney dysfunction (reflected by a lower eGFR) and systemic inflammation (reflected by a higher hs-CRP level) were independently associated with apathy in post-myocardial infarction patients." (PMID 28081723, 2017). "It was found that elevated levels of CRP had been related to patient instability and an increased risk of death, myocardial infarction, and the need for urgent revascularization." (PMID 29118378, 2017). "High levels of inflammatory markers like high-sensitivity C-reactive protein (hs-CRP) is able to predict risk of myocardial infarction." (PMID 27047809, 2016). "There was also a trend of reduced compliance in the common carotid (p = 0.24) and elevated hs-CRP (p = 0.10), a marker of inflammation and measure of myocardial infarction risk." (PMID 26779011, 2015). "An elevated serum level of CRP is associated with an adverse prognosis in patients with stable or unstable angina and following acute myocardial infarction." (PMID 26406989, 2015). "C-reactive protein (CRP) and IL-6 have been also identified as independent risk factors for future myocardial infarction." (PMID 25237578, 2014). "Specifically high CRP levels following myocardial infarction are associated with adverse outcomes, including left ventricular failure, and increased rates in cardiac death and ventricle rupture." (PMID 24808639, 2014). "Another score based on serum levels of CRP, fibrin degradation products, and heat shock protein 70 as predictors of future risk of death and myocardial infarction in patients with suspected or known CHD followed in 2013." (PMID 24808639, 2014). "The data of two large Danish population studies indicate that simultaneously elevated levels of CRP, fibrinogen and leukocyte count are associated with a two- to fourfold risk of major comorbidities (e.g. myocardial infarction, lung cancer) in COPD." (PMID 23924044, 2013). "CRP is an important acute phase protein with pro-inflammatory properties associated with atherogenesis, modulation of endothelial function and risk of acute myocardial infarction and it has been widely used as biomarker in air pollution studies." (PMID 24373585, 2013). "They found that SDNN of heart rate signals was significantly higher in the lower CRP quartile compared to the upper one, whereas associations were stronger for patients with a previous myocardial infarction and with significant coronary stenoses." (PMID 23847549, 2013). "Inflammatory biomarkers like CRP are also associated with cardiovascular diseases such as intracerebral hemorrhage and myocardial infarctions." (PMID 23924044, 2013). "Several studies revealed an independent association of high plasma CRP levels with adverse prognosis in acute myocardial infarction patients." (PMID 23936799, 2013). "In patients presenting with unstable angina or a myocardial infarction (MI), elevated CRP levels correlated with an increased risk of mortality at 14 days, independent of troponin levels." (PMID 22708908, 2012). "Further, a number of studies have confirmed that an elevated CRP is associated with an increased risk of ischemic vascular events, such as myocardial infarction." (PMID 23162475, 2012). "The CRP plasma level also is the best risk assessment in patients with either stable or unstable angina, long term after myocardial infarction, and in patients undergoing revascularization therapies." (PMID 24049653, 2012). "CRP is reported to be associated to CAD extent in myocardial infarction patients but nonetheless in unstable angina patients the correlation is reported to be weak." (PMID 19503842, 2009).
myocardial infarction (continued). "The fourth quartile of peak CRP was associated with poorer outcome in a univariate model with a hazard ratio of 3.0 (95% CI 1.9–5.0) for the occurrence of ischemic cerebral event, myocardial infarction and death, as compared to the first quartile." (PMID 19583836, 2009). "Peak CRP during the course of an acute myocardial infarction is associated with new cardiovascular events during long-term follow up." (PMID 19583836, 2009). "In patients with myocardial infarction, measured peak CRP is associated with new cardiovascular events." (PMID 19583836, 2009). "A meta-analysis involving 18,715 patients with acute myocardial infarction who underwent PCI demonstrated that elevated CRP levels were associated with an increased risk of in-hospital and short-term all-cause mortality, as well as significantly higher rates of cardiovascular mortality and MACE." (PMID 40918185, 2025). "Moreover, a sub-analysis from The Physicians’ Health Study showed the reduction associated with the use of aspirin in the risk of a first myocardial infarction appears to be directly related to the level of C-reactive protein." (PMID 38256497, 2024). "An association of systemic inflammation with cardiovascular diseases has been demonstrated, while baseline C-reactive protein (CRP) level has been shown to predict the long-term risk of a first myocardial infarction, ischemic stroke, and peripheral artery disease." (PMID 39198746, 2024). "Although lipoprotein(a) [Lp(a)] and high-sensitivity C-reactive protein (Hs-CRP) are closely associated with the mortality of acute myocardial infarction (AMI), their synergistic effect on the risk of death remains unknown." (PMID 38812817, 2024). "In a secondary analysis that aimed to investigate whether increased inflammation could explain the increased risk of cardiovascular disease, ischaemic heart disease, or myocardial infarction, all models were further adjusted for C reactive protein." (PMID 36936262, 2023). "In a study, it was determined that CRP level is a more powerful risk indicator than low-density lipoprotein-cholesterol in terms of cardiovascular events (myocardial infarction, cerebrovascular incidents, coronary revascularization, and death due to cardiovascular causes)." (PMID 36874319, 2023). "In addition to cTn, ultrasensitive C-reactive protein and B-type natriuretic peptide, which are more likely to be elevated in women with heart attacks, are less often included in clinical risk stratification." (PMID 37576112, 2023). "Analyses within the HUNT study population showed no strong associations between the allele scores for the genetic instruments for CRP and the potential pleiotropic factors such as BMI, smoking status, or a history of myocardial infarction, heart failure or rheumatoid arthritis." (PMID 37217205, 2023). "Connected with acute injury such as an acute myocardial infarction, this creates a vicious circle: the primary inflammation, induced by acute organ ischemia, causes a marked synthesis and secretion of IL-6 and, consecutively, CRP." (PMID 37626775, 2023). "In 2005, the research group around Ridker could show that death caused by myocardial infarction (MI) in patients with the acute coronary syndrome can be predicted by a high CRP (C-reactive protein) level." (PMID 36267276, 2022). "Increased CRP levels are associated with a greater extent of myocardial tissue damage, more severe LV dysfunction, and the occurrence of adverse events after myocardial infarction." (PMID 34884196, 2021). "Elevated CRP levels are associated with an increased risk of myocardial infarction, peripheral artery disease, sudden cardiac death and ischemic stroke, and, compared to other inflammatory biomarkers, it does not show diurnal variations, remaining stable for long periods of time." (PMID 34683106, 2021).
myocardial infarction (continued). "Besides, a high ratio of CRP/Alb indicated higher inflammation superimposed with malnutrition status and was inversely associated with the prognosis of patients with acute myocardial infarction." (PMID 34141715, 2021). "However, CRP is a parameter with low specificity, which shadows its diagnostic and prognostic value in acute myocardial infarction (AMI)." (PMID 34180324, 2021). "Furthermore, an association between CRP and HCy concentrations was reported in patients with acute myocardial infarction." (PMID 32599677, 2020). "The results of both AMORIS and INTERHEART studies showed that the apoB/apoA-I ratio was the most powerful predictor of myocardial infarction among all investigated parameters and importantly, like C-reactive protein, was able to detect subjects at higher risk even when LDL-C values were normal." (PMID 32449038, 2020). "A total of 10,061 patients with a previous myocardial infarction and showing inflammatory residual risk (CRP > 2 mg/L) under optimal CV-protective therapy were enrolled in this randomized, double-blind trial to receive canakinumab, a IL-1β inhibitory monoclonal antibody, or a placebo every 3 months." (PMID 31652822, 2019). "Indeed, the levels of C-reactive protein and interleukin-6 are elevated in patients with unstable angina and myocardial infarction and it has been shown that high levels are associated with a worse prognosis." (PMID 30935055, 2019). "Moreover, a polymorphism (Ala-87-Thr) in P2Y11 has been linked to increased risk of acute myocardial infarction and C-reactive protein blood levels." (PMID 30821687, 2019). "Inflammatory markers such as CRP, as well as endothelial dysfunction, are associated with cardiovascular risk factors and may predict cardiovascular events such as acute myocardial infarction and encephalic vascular accident." (PMID 31337127, 2019). "In subjects at intermediate risk of CVD, incorporation of CRP to a model of assessment of CV risk improves the prognostic power for myocardial infarction presentation, and could help prevent 1 additional CV event in 10 years from 400–500 screened subjects." (PMID 29552019, 2018). "Likewise, in some studies, vitamin D supplementation in patients with a history of myocardial infarction and elderly women with vitamin D deficiency was associated with a significant reduction in circulating levels of CRP." (PMID 29299042, 2017). "Here we also found that CRP decreased from 2010 to 2014, which may be associated with a decrease of the proportion of myocardial infarction as shown in another report." (PMID 28061763, 2017). "Notably, late POAF was associated with conventional risk factors of AF in the general population, whereas early AF was associated with low BMI, high CRP levels, and previous myocardial infarction." (PMID 26290873, 2015). "In this study we found genetic variants of TGFB1, FGB and CRP genes associated with myocardial infarction in discovery and replication groups of Russian descent from the Moscow region and the Republic of Bashkortostan (325/185 and 220/197 samples, correspondingly)." (PMID 26658659, 2015). "In addition, serum CRP levels can predict long-term risk of incidence of myocardial infarction, ischemic stroke, peripheral vascular disease and all-cause mortality." (PMID 26378571, 2015). "In addition, the Cholesterol and Recurrent Events Trial showed that elevated CRP levels are associated with major risk of coronary events after myocardial infarction." (PMID 23690772, 2013). "We therefore focused on Chennai based population with an attempt to understand if serum leptin concentration is associated with myocardial infarction, with particular emphasis on the relationship between serum leptin and inflammatory markers such as IL-6 and CRP in AMI condition." (PMID 22891684, 2012).